IL2 (interleukin 2)
Diseases named in the same sentence as IL2 in open-access papers (continued):
Sharing a sentence is not in itself a finding about the gene and the disease.
autoimmune disease (continued). "Disruption of different components in IL-2 signaling pathway, including CD25, CD122, Janus kinase 3, and STAT5, leads to compromised Treg generation associated with autoimmune diseases." (PMID 37436991, 2023). "Existing experimental studies have shown a very significant correlation between IL-2 cytokine levels and autoimmune diseases, especially psoriasis Therefore, therapies based on IL-2 regulatory T cells have been proposed." (PMID 37883350, 2023). "IL-2 contributes to a variety of autoimmune disorders, including the production of regulatory T cells, which suppress autoimmune disease." (PMID 35707129, 2022). "Instead of blocking IL-2 expression or responsiveness, direct administration of low dose IL-2 is intended to expand Treg in patients with AIH or other autoimmune diseases." (PMID 35903109, 2022). "Of note, however, IL-2 signaling is also critical for the development and function of CD4+CD25+FOXP3+ Tregs and the neutralization of IL-2 leads to induction of autoimmune diseases." (PMID 36510261, 2022). "This study revealed that low-dose IL-2 treatment resulted in increased proportions of Tregs, which was consistent with previous clinical trials on IL-2 therapy in other autoimmune diseases." (PMID 35360108, 2022). "Phosphatase tyrosine-protein phosphatase non-receptor type 2 (PTPN2) is a ubiquitously expressed negative regulator of the IL-2/IL-2R signalling cascade and has been investigated in different autoimmune diseases." (PMID 35526080, 2022). "Since there are prospects for use of IL-2 and IL-4 in the treatment of autoimmune diseases or infections, the respective contribution of T cell cytokine production to the pathogenesis of autoimmune diseases is still a matter of debate." (PMID 35155574, 2022). "An in vitro study showed that the blockade of the sCD25-mediated IL-2 signaling pathway enhances T-cell responses to the Th17 phenotype and promotes the development of autoimmune diseases." (PMID 35996408, 2022). "We are currently evaluating the homologous human fusion protein of the mouse thioredoxin/IL-2 fusion protein PDC as a potential drug candidate to treat several autoimmune diseases and, potentially, allergic asthma." (PMID 36569931, 2022). "A major drawback of IL-2 therapy in the context of autoimmune diseases is the activation of proinflammatory cells." (PMID 35790728, 2022). "We demonstrated here that IL-2 shaped gut microbiota, at both the taxonomic and functional levels, in 3 murine genetic backgrounds and in patients with autoimmune diseases." (PMID 35917175, 2022). "There have been several anecdotal reports of the successful use of low dose interleukin 2 (IL-2) to treat autoimmune diseases." (PMID 36569931, 2022). "Given that the therapeutic potential of IL-2 is currently being investigated in many autoimmune diseases, understanding its mode of action is of prime importance for rational drug development." (PMID 35917175, 2022). "Low-dose IL-2 therapy can be seen as a strategy to fight various autoimmune diseases complementary to Treg cell infusion." (PMID 36591309, 2022). "Low-dose IL-2 treatment has shown promising effects by expanding and activating Tregs in a number of clinical trials for several autoimmune diseases most prominently type 1 diabetes." (PMID 35526080, 2022). "In recent years, the use of low-dose interleukin-2 (IL-2) to treat autoimmune diseases has attracted widespread attention." (PMID 36244973, 2022). "Low-dose human interleukin-2 (hIL-2) treatment is used clinically to treat autoimmune disorders due to the cytokine’s preferential expansion of immunosuppressive regulatory T cells (Tregs)." (PMID 36261022, 2022). "Cytokine-based immunotherapies such as low-dose IL-2 prove potent in murine models of autoimmune disease and also human diseases such as systemic lupus erythematosus (SLE) and GvHD." (PMID 36429085, 2022).
autoimmune disease (continued). "The use of low dose of IL-2 (LDIL-2) in the treatment of autoimmune diseases is promising, but the efficacy and mechanism in SS therapy are still to be confirmed." (PMID 35665339, 2022). "Klatzmann describes IL-2 as “the corticosteroid of the 21st century” because low-dose IL-2 is well-tolerated in patients with 11 types of different autoimmune diseases (including BD) (Clinicaltrials.gov NCT01988506 and NCT04065672)." (PMID 33816637, 2021). "The TRANSREG clinical trial that comprised of patients with 11 autoimmune diseases also showed promising findings with low dose IL-2 administration." (PMID 35069220, 2021). "Furthermore, these studies offer a new interpretation for how impaired IL-2 production by T cells and single nucleotide polymorphisms in the IL-2 and IL-2 receptor genes, which are associated with various autoimmune diseases, affects autoimmune disease development." (PMID 33986755, 2021). "There have been many clinical trials using IL-2 that have demonstrated the importance of this cytokine in the promotion of clonal expansion of regulatory T cells and immunomodulation of autoimmune diseases." (PMID 34442052, 2021). "Recently, a low-dose IL-2 therapy induced the expansion of the Treg compartment in autoimmune disease patients including those with RA." (PMID 33916798, 2021). "An interesting study focusing on the safety and efficacy of low dose IL-2 in 11 autoimmune disease in 46 patients including SLE found significant Treg-expansion without effector T-cell activation." (PMID 35069220, 2021). "Th1 cells produce pro-inflammatory cytokines such as IFN-γ, IL-2, and IL-12, which stimulate phagocytosis, destroy pathogens, and are involved in organ-specific autoimmune diseases." (PMID 34945585, 2021). "Work done over the last fifteen years demonstrate the potential of leveraging the immunosuppressive properties of IL-2 to treat autoimmune disorders." (PMID 33986755, 2021). "In vivo administration of low doses of IL-2 can expand Tregs and ameliorate disease in multiple autoimmune disease models in mice." (PMID 34324441, 2021). "In numerous autoimmune diseases, there is a decrease in the numbers and function of Treg cells that is restored by exogenous low doses of IL-2 in mice and humans." (PMID 34685775, 2021). "IL-2/JES6 are effective in the treatment of autoimmune diseases and in protecting against rejection of pancreatic islet allografts." (PMID 34932467, 2021). "With low dose and mutein IL-2 therapy currently advancing through clinical trials as a method for in vivo Treg expansion in autoimmune diseases and transplantation, there is now an attractive argument for exploring IL-33 therapy for the same indications." (PMID 33314772, 2021). "Several investigators have tried to utilize the ability of IL-2 to expand Tregs for protection in autoimmune diseases." (PMID 35069220, 2021). "IL-2 is essential for the development and maintenance of Treg cells, which prevent the development of autoimmune disease." (PMID 34116715, 2021). "These animal studies provided important rationales for the use of low-dose IL-2 therapy in the treatment of this organ specific autoimmune disease." (PMID 33868284, 2021). "Understanding the role of the IL-2 – IL-2R pathway in autoimmune diseases like MS is further complicated by the existence of soluble (s)IL-2R, a receptor component most likely released by shedding from the cell surface of activated immune cells." (PMID 35005590, 2021). "Early studies show that exogenous IL-2 supplementation prevents disease progression and contributes to inducing immunosuppression in mice with established autoimmune diseases, including Type I diabetes, EA, experimental myasthenia, and lupus." (PMID 33986755, 2021). "Recently, low-dose IL-2 therapy was applied as a new clinical approach for autoimmune diseases that takes advantage of the selective activity of low-dose IL-2 on Treg cells." (PMID 33916798, 2021).
autoimmune disease (continued). "While IL-2 plays a beneficial role in preventing autoimmune disease development, high levels of IL-2 lead to capillary leak syndrome and are associated with nosocomial sepsis." (PMID 32973504, 2020). "Treg cell survival and function is dependent on the cytokine, interleukin-2 (IL-2), which is required for maintaining effective levels of functional Treg cells in autoimmune disease (AID)." (PMID 33072105, 2020). "In summary, we have shown that PPP2R2D, a regulatory subunit of PP2A, suppresses the production of IL-2 and Treg activity, and its specific targeting should increase IL-2 production and Treg activity in autoimmune diseases." (PMID 32897879, 2020). "Given the important role of IL-2 in Treg survival and expansion and the better availability of IL-2 in vitro, clinical trials of low-dose IL-2 in various autoimmune diseases have been undertaken." (PMID 33117375, 2020). "Our findings are in line with the idea that human ‘latent’ Tregs can be revealed after a short‐term in vitro exposure to IL‐2 also from patients with autoimmune diseases." (PMID 33376595, 2020). "Given its role in Foxp3+ Treg biology, providing IL2 to Foxp3+ Tregs as an intervention for autoimmune diseases had been tested in clinic over the years." (PMID 32269069, 2020). "The results showed that CBP EVs downregulated human IL-2, IFN-γ, and IL-6, which are associated with the differentiation of Th1 and Th17 cells and the development of autoimmune diseases." (PMID 32308765, 2020). "Low-dose IL-2 in the treatment of autoimmune diseases including SLE, rheumatoid arthritis, and multiple sclerosis is in clinical trials." (PMID 32897879, 2020). "PTPN2 is a negative regulator in the IL-2 signalling cascade and several SNPs in the PTPN2 gene region have been linked to different autoimmune diseases including T1D, rheumatoid arthritis and Crohn’s disease." (PMID 33193091, 2020). "More caution is being exercised regarding similar trials using low-dose IL-2 in autoimmune diseases, since in contrast to HSCT or solid organ transplantation, autoimmune patients are not lymphopenic and are likely to produce IL-2 themselves." (PMID 30853957, 2019). "Low-dose IL-2 therapy intends to restore Treg homeostasis and early phase clinical trials suggest that this treatment is efficacious in large variety of autoimmune diseases including SLE." (PMID 31614462, 2019). "Several single-nucleotide polymorphisms (SNPs) situated in IL2/IL21 region including: rs13151961, rs13119723, rs6840978, and rs6822844 have proven to be significantly associated with many autoimmune disorders, such as RA." (PMID 31366568, 2019). "Further trials in SLE and other autoimmune diseases specifically designed to investigate the effect of low-dose IL-2 on different stages of disease will be paramount to address these questions." (PMID 31781109, 2019). "It is important to note that the presence of IL-2 is required for the function of exosomes, with implications for the initiation of the immune response and autoimmune disease." (PMID 31275303, 2019). "Aldesleukin is a human recombinant form of IL-2 that has been used therapeutically in several autoimmune diseases." (PMID 30224390, 2018). "So, in this part, we summarize the clinical trials of low-dose IL-2 treatment in autoimmune diseases." (PMID 29527328, 2018). "Recombinant IL-2, aldesleukin, has been approved for the treatment of cancers and has been successful in the immune modulation of autoimmune diseases, such as type 1 diabetes and vasculitis." (PMID 30347791, 2018). "The immunostimulatory cytokine Interleukin-2 (IL-2) has shown potency for autoimmune disease treatment as well as adverse effects, which deserve more investment to develop its therapeutic potential." (PMID 29558421, 2018). "Genetic studies in autoimmune disease identified polymorphisms in IL-2 pathway genes encoding IL-2RA (CD25), IL-2, CTLA-4 and PTPN2 as key drivers in autoimmune disease susceptibility." (PMID 30446251, 2018).
autoimmune disease (continued). "This study provides further understanding of IL-2-mediated therapeutic application in autoimmune diseases." (PMID 30150979, 2018). "The researchers summarized data from proof-of-concept clinical trials, which showed that, at low doses, IL-2 is well tolerated and induces regulatory T cells to address immune imbalances in patients with lupus, type 1 diabetes and other autoimmune disorders." (PMID 29527328, 2018). "We also summarize proof-of-concept clinical trials which have shown that low-dose IL-2 can control autoimmune diseases safely and effectively by specifically expanding and activating Treg." (PMID 29527328, 2018). "Fine-tuning IL-2 signaling pathways has received great attention in the treatment of cancer and autoimmune diseases." (PMID 30150979, 2018). "Over the past decade, the concept of targeting cytokines to treat autoimmune diseases has evolved at a rapid pace, such as some medicines approved by the drug administration to target IL-1β, IL-5, IL-6, IL-2, TNF-α, and IFN-γ." (PMID 29250557, 2017). "IL-2 is the key cytokine in the initiation and maintenance of T cell response, and modulation of IL-2 expression can alter the outcome of autoimmune diseases." (PMID 29050214, 2017). "Using IL-2 to preferentially expand Treg cells constitutes an area of intense focus related to autoimmune disease." (PMID 29123649, 2017). "Aldesleukin (Proleukin; recombinant human IL-2), which is administered at high doses to activate the immune system in cancer immunotherapy, is now being repositioned to treat inflammatory and autoimmune disorders at lower doses by targeting Tregs." (PMID 27727279, 2016). "Treg essentially depend on IL-2 for their peripheral maintenance and suppressive activity and their number and activity can be therapeutically manipulated by low-dose IL-2 and particular IL-2/anti-IL-2 complexes to control autoimmune diseases and inflammation." (PMID 27065076, 2016). "For instance, IL-2R-beta or IL-2R–alpha chain knockout mice develop autoimmune disease and blocking of IL-2 by in vivo treatment with monoclonal antibody to IL-2 accelerates autoimmunity in mice." (PMID 27242702, 2016). "In the group of patients treated with ipilimumab prior to HD IL-2 6 patients (11 %) reported evidence or autoimmune disease." (PMID 27660706, 2016). "Clinical use of STAT5-activating cytokines and growth factors (e.g. IL-2, erythropoetin) is now commonplace and the recent approval of Jak3 inhibitors for the treatment of autoimmune disease and malignancy points to sustained interest in this pathway." (PMID 26999798, 2016). "Therapeutic uses of IL-2/anti-IL-2 antibody complexes have been reviewed for cancer and autoimmune diseases, treatment of tumors, anti-bacterial and anti-viral infections, multiple sclerosis, and transplantation tolerance." (PMID 26870966, 2016). "Later it was recognized that IL-2 has also a critical function in down-modulating immune-responses as mice with a defective IL-2 pathway developed lymphoproliferative and autoimmune disorders." (PMID 26731275, 2016). "In autoimmune diseases, impaired IL-2 signaling is thought to affect the number and function of Tregs." (PMID 26834735, 2015). "In the present review, we discuss recent reports describing efficacy and side effects with LD IL-2 treatment in preclinical and clinical experiments of select autoimmune diseases." (PMID 26793191, 2015). "Increased concentrations of serum soluble IL-2 have been found in patients with diverse diseases, including lymphoma, leukemia, sarcoidosis, tuberculosis, viral infection, autoimmune diseases, and organ allograft rejection." (PMID 26115010, 2015). "Recently, the first results on immunomodulation with low-dose IL-2 in other autoimmune diseases have been published, showing efficacy on upregulation of Tregs and improved clinical outcome." (PMID 26350950, 2015).
autoimmune disease (continued). "More recently, paracrine IL-2 signaling towards Treg cells was identified as essential to prevent autoimmune diseases, possibly due to competition with autocrine self-activation." (PMID 25923703, 2015). "Recent studies expanding Tregs in vivo with low-dose IL-2 achieved major clinical successes highlighting the potential to optimize this pleiotropic cytokine for inflammatory and autoimmune disease indications." (PMID 25457307, 2015). "The current strategy of low-dose IL-2 therapy for autoimmune diseases consists of daily subcutaneous administration of recombinant IL-2." (PMID 25629163, 2015). "There is evidence from a mouse diabetes model showing the importance of Treg suppression and IL-2 consumption in an autoimmune disease." (PMID 26220086, 2015). "The disrupted balance between regulatory and effector T cells (Tregs and Teffs, respectively) is a characteristic of autoimmune diseases, and is dependent on homeostatic cytokines, including IL-2." (PMID 25322151, 2014). "Deficiency of IL-2, IL-2Rα, or IL-2Rβ in mice leads to development of lethal autoimmune diseases, which has been attributed to defects in IL-2 signaling within the Treg cells." (PMID 24416451, 2014). "In striking contrast are the doses of IL-2 used in therapy of autoimmune diseases; IL-2 single doses ranged from 0.33 × 106 to 4.5 × 106 IU, and the cumulative dose range of IL-2 was 1.65 × 106 to 100.2 × 106 IU." (PMID 25322151, 2014). "We chose the rs6822844 IL2-IL21 gene cluster polymorphism because of its promising character in studies on autoimmune diseases and the involvement of IL-2 and IL-21 in the rejection process." (PMID 25377634, 2014). "The significant role of IL-2 played in Treg generation and homeostasis has motivated scientific research on developing IL-2-based immunotherapy for autoimmune diseases." (PMID 27574641, 2014). "All preclinical and clinical studies discussed emphasize the potential therapeutic benefit of low-dose IL-2 therapy of autoimmune disorders." (PMID 25322151, 2014). "Given the central role of IL-2 in Treg homeostasis, there was considerable interest in exploring its potential therapeutic effect in the mouse models of different autoimmune diseases." (PMID 25322151, 2014). "Although low-dose IL-2 has an implicit potency to prevent and/or treat human autoimmune diseases, some questions still remain uncertain." (PMID 25322151, 2014). "In this review, we discuss the role of IL-2 in pathogenesis of autoimmune diseases, particularly regarding its positive considerable impact on Treg cell fitness and suppressive function." (PMID 25322151, 2014). "Actually, inherent defects in the IL-2 signaling pathway and/or levels leading to Treg compromised function and numbers as well as Th17 expansion have been attributed to autoimmune disorders." (PMID 25322151, 2014). "IL-2 promotes development of regulatory T cells and confers protection from autoimmune disease whereas IL-21 promotes differentiation of Th17 cells and is implicated in the development of several autoimmune diseases." (PMID 23676143, 2013). "Thus, we hypothesized that decreased response to IL-2 may be a common phenotype of subjects who have autoimmune diseases associated with variants in the IL2RA locus, including T1D and MS, particularly in cells expressing the high affinity IL-2R alpha chain (IL-2RA or CD25)." (PMID 24376757, 2013). "In fact, SNPs located within the extended murine IL2 promoter, which associate with autoimmune disease, were found to alter the gene transcription in CD4+ T cells and diminished interleukin-2 synthesis was reported for a susceptible haplotype in NOD mice." (PMID 24154763, 2013). "Surprisingly, in IL-2 or IL-2R knockout mice, T cells develop, and these mice acquire a lymphoproliferative syndrome and spontaneous autoimmune disease." (PMID 21647403, 2011).